COL11A1 (collagen type XI alpha 1 chain)
Diseases named in the same sentence as COL11A1 in open-access papers (continued):
Sharing a sentence is not in itself a finding about the gene and the disease.
breast carcinoma (continued). "Consequently, conclusions regarding the prognostic or predictive role of COL11A1 in breast cancer should be considered preliminary until validated in prospective, standardized clinical cohorts." (PMID 41462920, 2025). "In our extended experiment, we found that high level of COL11A1 contributed to reduced sensitivity of CDK4/6 inhibitors in ER+ breast cancer cells, suggesting inhibition of COL11A1 may enhance the efficacy of palbociclib, abemaciclib and ribociclib." (PMID 38806505, 2024). "Consistently, the expression of COL11A1 was upregulated in luminal-breast cancer." (PMID 38806505, 2024). "We found that COL11A1 was highly expressed at both the transcriptome and protein levels in breast cancer tissues and could serve as a marker of a poor prognosis." (PMID 36389832, 2022). "Further immune infiltration related survival analysis suggested that COL11A1 may affect the prognosis of breast cancer patients by affecting the infiltration level of some immune cells." (PMID 36160004, 2022). "In addition, Liu inhibited the progression of estrogen receptor-positive breast cancer by constructing MiR-4458-loaded gelatin nanospheres targeting COL11A1 to block the DDR2/SRC signaling pathway." (PMID 36160004, 2022). "In addition, we explored potential evidence that COL11A1 regulates immune cell infiltration in breast cancer TME." (PMID 36160004, 2022). "COL3A1, COL11A1, and FBN1 are associated with maintaining a cancer stem-like phenotype in various cancers and therefore may be of interest in breast cancer." (PMID 35755802, 2022). "Another study has found that microRNA let-7b is a tumor suppressor, and the binding of CDX2 to let-7b can promote the transcription of let-7b and inhibit the expression of COL11A1, thereby reducing the proliferation, invasion, and migration of breast cancer cells." (PMID 35847935, 2022). "Interestingly, the prognostic value of COL11A1 in patients with different molecular subtypes of breast cancer also showed significant differences." (PMID 36160004, 2022). "For those who with different HER-2 expression profiles, high expression of COL11A1 was associated with poor OS only in breast cancer patients without HER-2 overexpression." (PMID 36160004, 2022). "Overall, our results suggest that COL11A1 may be a potential new prognostic biomarker for breast cancer." (PMID 36160004, 2022). "Our Immunohistochemistry (IHC) results demonstrate that COL11A1 could express high in breast cancer tissues while compared with normal tissues in clinical samples." (PMID 36389832, 2022). "In order to further confirm the difference of COL11A1 expression between breast cancer and Adjacent tissues, 20 pairs of paired samples from breast cancer patients were detected, and the mRNA transcription and protein expression levels were detected by RT-qPCR and immunohistochemistry." (PMID 36160004, 2022). "However, COL11A1 is well known to be upregulated in several cancers with epithelial cells, with a median fold change of 2.54, increasing up to 5.3 in breast cancer, followed by mesothelioma and pancreatic adenocarcinoma." (PMID 36293285, 2022). "We believe that COL11A1 may play an important role in the occurrence and development of breast cancer." (PMID 36160004, 2022). "Wang reported that CDX2 overexpression could alleviate breast cancer progression by upregulating microRNA let-7b and inhibiting COL11A1 expression." (PMID 36160004, 2022). "Furthermore, we found that in breast cancer patients with histological grades I, II, and III, COL11A1 was only associated with poor prognosis in patients with histological grade III." (PMID 36160004, 2022). "In addition to the elevated expression levels of COL11A1 in breast cancer tissues compared with normal breast tissues (There were also significant differences in COLL11A1 expression levels among breast cancer subtypes." (PMID 36160004, 2022).
breast carcinoma (continued). "COL11A1 is at a high expression level in adenocarcinoma and squamous cell lung cancer compared with that in corresponding normal lung tissue, and also is involved in lymphatic metastasis of breast cancer." (PMID 35669376, 2022). "Therefore, we believe that COL11A1 is a very potential target for diagnosis and treatment of breast cancer." (PMID 36160004, 2022). "All these results implied that COL11A1 could be involved in the tumor immune evasion process and could act as a poor immune-related biomarker in breast cancers." (PMID 36389832, 2022). "COL11A1 is a potential therapeutic target in breast cancer and may be involved in the tumor immune infiltration; its high expression is strongly associated with poor prognosis." (PMID 36389832, 2022). "Overexpression of miR-139-5p or silencing of COL11A1 could inhibit the proliferation of breast cancer cells and promote apoptosis." (PMID 35847935, 2022). "COL11A1 is also thought to be a potential prognostic biomarker for breast cancer." (PMID 35669376, 2022). "Similarly, in the case of breast cancer, the evaluation of the circulating level of COL11A1, COL10A1, and COMP (collagen oligomeric matrix protein) can discriminate between a malign and a benign disease." (PMID 36293285, 2022). "Accordingly, we propose that COL11A1 may be a very promising new immunotherapy-related target for breast cancer." (PMID 36160004, 2022). "miR-139-5p and miRNA let-7b regulate COL11A1 in breast cancer cells." (PMID 34944877, 2021). "miR-139-5p overexpression or COL11A1 silencing could inhibit the proliferation of breast cancer cells and promote apoptosis." (PMID 34944877, 2021). "Additionally, microRNAs miR-145, miR-139-5, (and potentially miR-29) as well as the growth factor FGF-14 negatively regulate COL11A1 expression in ovarian fibroblasts, breast cancer cells, and lung cancer cells, respectively." (PMID 33668097, 2021). "COL11A1 has also been regarded as a promising prognostic biomarker for breast cancer." (PMID 31938021, 2020). "In addition, COL11A1 is differentially expressed between primary breast cancers that metastasize and their corresponding lymph node sites where its expression seems that is no longer needed." (PMID 26466668, 2015). "The detection of such quantitative changes in COL11A1 expression could lead to novel approaches regarding prognostic and/or predictive tools for breast cancer." (PMID 26466668, 2015). "We quantified COL11A1 mRNA levels in 30 pairs of adjacent normal breast and primary breast cancer tissues, 30 pairs of primary breast cancer and lymph node metastasis tissues, 30 benign tumor tissues, and 107 primary breast cancer tissues using real-time reverse transcription (RT)-PCR." (PMID 39845732, 2025). "In addition to being positively correlated with other prognostic ECM proteins such as COL11A1, serum levels of α1 chain of collagen types X and XI are elevated in both benign breast disease (n = 42) and breast cancers (n = 52) compared to healthy controls (n = 50) by ELISA assays." (PMID 39716322, 2024). "Therefore, we speculate that COL11A1 may be involved in the biological process of breast cancer tumor immunity, but this conclusion still needs further biological experiments to prove." (PMID 36160004, 2022). "Therefore, COL11A1 may be a potential biomarker related to diagnosis, treatment and prognosis assessment of breast cancer." (PMID 36160004, 2022). "Therefore, more precise mechanisms of COL11A1 should be explored in breast cancers." (PMID 36389832, 2022). "Although previous studies have pointed out that abnormal expression of COL11A1 can change the biological characteristics of breast cancer cells, there is no report on the involvement of COL11A1 in the occurrence and development of breast cancer and its corresponding underlying mechanisms." (PMID 36160004, 2022).
breast carcinoma (continued). "However, there are few studies on COL11A1 in human breast cancer." (PMID 36160004, 2022). "During the experiment, we found that the two conclusions were consistent that the expression level of COL11A1 in the primary breast cancer was significantly lower than that in normal breast tissue or paracancerous tissue, whether in independent samples or paired samples." (PMID 36160004, 2022). "Given about that COL11A1 is closely related to the occurrence and development, drug resistance and poor prognosis of many kinds of tumors, there is only limited evidence that COL11A1 may also be involved in the pathogenesis of breast cancer." (PMID 36160004, 2022). "We confirmed that the expression of KIF4A, UBE2C and COL11A1 was distinctly increased in BC specimens compared with normal breast specimens, while the expression of SFRP1, SAA1 and RBP4 was distinctly decreased in breast cancer specimens." (PMID 35646102, 2022). "However, there were no reports on the direct association between COL11A1 and breast cancer in the study." (PMID 31938021, 2020). "Disease-specific survival discrepancy was observed comparing breast cancer patients of the upper and lower quartile of the collagen family (COL2A1, COL11A1, COL6A1, COL6A2), THBS1 and LUM gene expression signature (log-rank test, P = 0.06)." (PMID 40927672, 2025). "Second, the TCGA BRCA dataset (n = 821) with PAM50 subtypes called by RNAseq was used to validate the differentially expression of COL2A1, COL11A1, COL6A1, COL6A2, THBS1 and LUM among four breast cancer molecular subytpes in an independent cohort." (PMID 40927672, 2025). "Among these key genes COL11A1, MMP11 and COL10A1 were highly expressed and PCOLCE2, LAMA2, TMTC1, ADAMTS5, TIMP4, and RSPO3 were having lower expression levels in breast cancer samples." (PMID 37238942, 2023). "The genes namely COL11A1, MMP11 and COL10A1 were found up regulated and PCOLCE2, LAMA2, TMTC1, ADAMTS5, TIMP4 and RSPO3 were found down regulated in breast cancer." (PMID 37238942, 2023). "In conclusion, our study identified nine key regulators, of which COL11A1, MMP11 and COL10A1 were up regulated and PCOLCE2, LAMA2, TMTC1, ADAMTS5, TIMP4 and RSPO3 were down regulated in breast cancer samples as compared to control samples." (PMID 37238942, 2023). "The genes namely COL11A1, MMP11 and COL10A1 were found up-regulated and PCOLCE2, LAMA2, TMTC1, and TIMP4 were found down-regulated in breast cancer cell lines also." (PMID 37238942, 2023). "While collagen type I is well described as having a role in cancer cell proliferation, drug resistance, and motility, the matrix proteins such as COL3A1, COL11A1, FBN1, and MFAP2 are less explored in breast cancer." (PMID 35755802, 2022). "However, the role of COL11A1 in the TME of breast cancers remains unclear." (PMID 36389832, 2022). "More recently, high levels of circulating COL11A1 has been identified in patients with NSCLC and breast cancer, which correlated with increased aggressiveness of the disease." (PMID 33668097, 2021). "The elevated expression of IBSP, COL11A1, MYBL2 and UBE2C in breast cancer has previously been reported to directly correlate with tumor progression." (PMID 27359054, 2016). "The study also could be extended to a larger number of breast cancer tissues and a significant number of normal tissues so that it could verify the results of earlier studies in relation to increased or no expression of COL11A1 mRNA and its variants in breast cancer." (PMID 26466668, 2015). "Although COL11A1 is not yet recognized as a clinically validated biomarker for resistance to immune checkpoint inhibitors (anti–PD-1/PD-L1) in breast cancer, it remains of scientific interest." (PMID 41462920, 2025). "We also evaluated the effect of COL11A1 on endocrine therapeutic responses of breast cancer patients by ROC plotter server, and demonstrated that COL11A1 expression was significantly elevated in the non-responder group compared to the responder group." (PMID 38806505, 2024).
breast carcinoma (continued). "We also investigated the COL11A1 effect on the responsiveness of the cells to CDK4/6 inhibitors including palbociclib, abemaciclib and ribociclib, which are now frequently used in treating ER+ breast cancer patients." (PMID 38806505, 2024). "COL1A1, COL1A2, COL11A1, and COL5A1 have been reported to regulate several cancers, including colorectal cancer, esophageal cancer, hepatocellular carcinoma, renal cell carcinoma, breast cancer, and gliomas." (PMID 38639039, 2024). "In addition to the major fibrillar collagen class, many minor fibrillar collagens, including those (COL11A1, COL5A1, and COL5A2) have reported prognostic value in breast cancer." (PMID 39716322, 2024). "The overexpression of COL11A1 and COL1A1 plays a crucial role in the metastasis of gastric, breast, and colorectal cancers, as well as in the development of tamoxifen resistance in breast cancers." (PMID 39682235, 2024). "Importantly, increases in COL8A1, BGN, COL11A1, POSTN, MMP11 and SORCS2 and decreased LTBP4, PCOLCE2, LRRC17 and SDK1 have been identified in CAS and CAFs from human breast cancer and are consistently perturbed in stroma of canine and human mammary cancer." (PMID 37391533, 2023). "Although no studies have reported the relationship between COL11A1 and breast cancer tumor immunity, two gene groups closely related to COL11A1 are significantly enriched in immune-related biological processes." (PMID 36160004, 2022). "Among them, compared with PR and HER-2 negative breast cancer tissues, PR and HER-2 positive breast cancer tissues have higher expression levels of COL11A1." (PMID 36160004, 2022). "Secondly this study did reveal the correlation between COL11A1 and breast cancer tumor immunity and confirmed the main immune cell subsets regulated by COL11A1, but we did not elaborate on its specific regulatory mechanism." (PMID 36160004, 2022). "In summary, this study has improved our understanding of the relationship between COL11A1 and breast cancer, but this study is not absolutely perfect." (PMID 36160004, 2022). "Notably, the combination of COL11A1, COMP, and COL10A1 was identified as a promising biomarker to differentiate breast cancer patients from the benign controls." (PMID 33435254, 2021). "Potential biomarkers for canine and human mammary carcinoma may be EMT-related genes such as COL11A1, COL8A2, and ADAM12 which are overexpressed in mammary carcinoma." (PMID 33282730, 2020). "COL11A1 and COL10A1 have recently been proposed as markers to discriminate between breast cancer and healthy tissues and could be helpful in the diagnosis of suspicious breast nodules." (PMID 30835723, 2019). "In a The Cancer Genome Atlas (TCGA) comparative study between normal breast tissue (n = 113) and breast tumors (n = 1109), COL11A1, COL12A1, COL1A1, COL1A2, COL5A1, and COL5A2 transcripts were upregulated in breast cancer and could discriminate between the two breast tissues." (PMID 39716322, 2024). "Interestingly, the expression of ER and PGR did not affect the effect of high COL11A1 expression on OS in breast cancer patients." (PMID 36160004, 2022). "Subsequently, we studied the relationships between differential expression of COL11A1 and the corresponding T status, N status, M status, clinical stage, ER status, PR status, HER-2 status, PAM50 status, histological types and menopause status in breast cancer patients." (PMID 36160004, 2022). "Therefore, circulating COL11A1, COMP, and COL10A1 could be used as biomarkers to diagnose breast cancer." (PMID 33435254, 2021). "In order to realize the target genes of let-7b, highly-expressed genes in breast cancer were predicted using the TargetScan database and breast cancer-related microarrays including GSE109169, GSE3744, and GSE26910, which suggested that the COL11A1 gene may be a target of let-7b." (PMID 31938021, 2020).
breast carcinoma (continued). "Human breast cancer epithelial cell line MCF-7 was treated with over-expressed CDX2, let-7b mimic, shRNA against COL11A1 and their negative controls." (PMID 31938021, 2020). "Although this interaction is not known to regulate COL11A1 function, binding, or signaling, OSM has been noted to be immobilized to type XI collagen induced signal transducer and activator of transcription (STAT) signaling in the breast cancer cell line T47D." (PMID 35847935, 2022). "Although this interaction is not known to regulate COL11A1 function, binding, or signaling, OSM immobilized to type XI collagen induced Signal Transducer and Activator of Transcription (STAT) signaling in the breast cancer cell line T47D." (PMID 33668097, 2021).